BAGE2 (BAGE family member 2 (pseudogene))
Description:
Unknown. Candidate gene encoding tumor antigens.
Synonyms: CT2.2
Gene: Transcribed unprocessed pseudogene on chromosome 21 (10,454,134 to 10,516,431, forward strand). Ensembl gene ENSG00000187172.
Subcellular location: Secreted
Diseases named in the same sentence as BAGE2 in open-access papers:
BAGE2 is named in the same sentence as 5 diseases in open-access papers, as found by Europe PMC text mining. Sharing a sentence is not in itself a finding about the gene and the disease. The quoted sentences say what the papers report.
lung adenocarcinoma (2 papers, 2018 to 2021). A carcinoma that arises from the lung and is characterized by the presence of malignant glandular epithelial cells. "We believe that BAGE2 mutation appears at the AAH stage, and its mutation abundance increases gradually during the development of lung adenocarcinoma." (PMID 33442956, 2021). "DST, FRG1B and BAGE2 are thus candidate driver genes for lung adenocarcinoma and good targets for follow-on experiments." (PMID 30541428, 2018). "The BAGE2 gene may be further explored as an important site for immunotherapy for lung adenocarcinoma in the future." (PMID 33442956, 2021). "However, no studies have so far been published on the biological mechanism of BAGE2 in lung adenocarcinoma." (PMID 33442956, 2021). "Importantly, three of the non-COSMIC predictors included in the top ten for the C2.CP collection (DST, FRG1B and BAGE2) are also in the top ten for the C6 collection and none of the three has an established association with lung adenocarcinoma." (PMID 30541428, 2018).
melanoma (2 papers, 2018 to 2025). A malignant, usually aggressive tumor composed of atypical, neoplastic melanocytes. "BAGE2, a long noncoding RNA (lncRNA) gene often related to melanoma, had the highest frequency of somatic mutations (67 mutations)." (PMID 40622919, 2025). "BAGE2 was a candidate gene that encoded tumor antigens and was the most frequently mutated smRMG, with a mutation rate of 59% in melanoma (UVM)." (PMID 30107644, 2018).
osteosarcoma (1 paper, 2021). A usually aggressive malignant bone-forming mesenchymal neoplasm, predominantly affecting adolescents and young adults. "Mutations in BAGE2 have been hypothesized to play a role in immune evasion in osteosarcomas." (PMID 33980253, 2021).
cancer (2 papers, 2024 to 2025). A tumor composed of atypical neoplastic, often pleomorphic cells that invade other tissues. "What is more, our study identified three genes (BAGE2, HAVCR1P1, and LINC01667) as potential biomarkers to discriminate healthy individuals from multiple types of cancers in general." (PMID 38414068, 2024).
tumor (2 papers, 2018 to 2019). "GPR98 is among the 25 most frequently mutated genes in all tumor types surveyed; its mutational frequency is similar to that of genes (e.g., BAGE2) that are mutational hotspots." (PMID 31765370, 2019).